MIR1207 (microRNA 1207)
Synonyms: hsa-mir-1207; MIRN1207
Gene: MicroRNA gene on chromosome 8 (128,049,152 to 128,049,238, forward strand). Ensembl gene ENSG00000221176.
Gene Ontology:
Biological process: miRNA-mediated post-transcriptional gene silencing
Cellular component: RISC complex
Diseases named in the same sentence as MIR1207 in open-access papers:
MIR1207 is named in the same sentence as 1 disease in open-access papers, as found by Europe PMC text mining. Sharing a sentence is not in itself a finding about the gene and the disease.
MIR1207 shares sentences with these, for which no sentence is quoted: endometrial cancer (1 paper).